PCSK9 (proprotein convertase subtilisin/kexin type 9)
Diseases named in the same sentence as PCSK9 in open-access papers (continued):
Sharing a sentence is not in itself a finding about the gene and the disease.
cancer (continued). "Additionally, proprotein convertase subtilisin/kexin type 9 (PCSK9) regulates lipoprotein homeostasis and facilitates cancer metastasis partially through lactylation." (PMID 40849305, 2025). "There is ongoing investigation into whether PCSK9 inhibition affects immune responses in cancer patients receiving immunotherapy." (PMID 40227756, 2025). "In addition, PCSK9 inhibition using siRNA, gene knockout, or anti-PCSK9 vaccination promotes apoptosis in in vitro cancer models." (PMID 40511612, 2025). "PCSK9 expression had been reported in different cancer types." (PMID 40362754, 2025). "This highlights PCSK9’s potential involvement in LSEC activation by cancer stem cells." (PMID 40563628, 2025). "PCSK9 has shown an aberrant expression pattern in several tumors and has been proved to play an oncogenic role in breast, prostate, colon, gastric, lung, skin, and other cancers." (PMID 40362754, 2025). "This review summarizes current knowledge on the biological functions of PCSK9 in cancer and examines how these pathways may have implications for therapeutic resistance." (PMID 41594607, 2025). "Elevated PCSK9 expression has been associated with poor prognosis, drug resistance, and reduced progression-free survival (PFS) in certain cancers, highlighting its dual role in cancer progression and immune modulation." (PMID 40370434, 2025). "However, more studies are required to determine the long-term impact of PCSK9 inhibition on cancer progression and outcomes in patients undergoing active cancer treatment." (PMID 40227756, 2025). "While preclinical studies suggest a link between PCSK9 inhibition and reduced tumor growth, robust clinical trials are needed to clarify inclisiran’s potential role in oncological prevention and its broader impact on cancer-related metabolic pathways." (PMID 40364115, 2025). "For instance, the role of PCSK9 in other cancer types remains to be explored." (PMID 39872986, 2025). "Given that PCSK9 promotes peripheral immune tolerance and inhibits cancer cell immune recognition, the use of PCSK9 inhibitors may potentially enhance the efficacy of ICIs." (PMID 41009661, 2025). "Similarly, PCSK9 inhibitors such as evolocumab and alirocumab can synergize with anti‐PD‐1 therapies to inhibit cancer growth." (PMID 40145543, 2025). "Furthermore, targeting cholesterol metabolism, such as with statins or proprotein convertase subtilisin/kexin type 9 (PCSK9) inhibitors, shows potential in cancer therapy." (PMID 38768058, 2024). "In addition to its function in cholesterol metabolism, PCSK9 is also involved in the cell cycle, inflammation, and apoptosis and is overexpressed in both differentiating cells and numerous human cancer cell lines." (PMID 38509261, 2024). "Considering the elevated risk to develop atherosclerotic plaques and consequently atherosclerotic cardiovascular disease in cancer patients who underwent ICIs therapy, PCSK9 inhibitors may increase their OS by reducing LDL-C." (PMID 38509261, 2024). "However, no comprehensive analysis has been conducted to explore the role of PCSK9 in a pan-cancer perspective." (PMID 38600469, 2024). "We found that PCSK9 mediates the positive immune microenvironment in BRCA and THCA; however, the suppressive immune microenvironment in both STAD and TGCT, suggesting that blocking PCSK9 could benefit some cancer types." (PMID 38600469, 2024). "PCSK9 has been reported to regulate T-cell activation and infiltration in cancer." (PMID 38600469, 2024). "Several clinical trials of PCSK9 inhibitors in cancer have been carried out." (PMID 39282119, 2024). "Notably, PCSK9 has been implicated in the process of EMT, a critical mechanism in tissue remodeling, cancer metastasis and histological fibrosis." (PMID 39722825, 2024). "Importantly, anti-cancer and immune-stimulating characteristics of PCSK9 inhibitors have emerged from recent preclinical and clinical findings." (PMID 38509261, 2024).
cancer (continued). "Thus, we comprehensively examined the expression of PCSK9 in 33 different tumors based on TCGA data to investigate the correlation between PCSK9 and cancer progression." (PMID 38600469, 2024). "This could further pave the way for launching more clinical trials to examine different strategies to inhibit PCSK9 in cancer patients." (PMID 38185721, 2024). "As PCSK9 may facilitate the immunosuppressive TME in multiple cancers according to bioinformatic analysis, we aim to explore the immunoregulatory role of PCSK9 inhibition in vivo." (PMID 38600469, 2024). "Furthermore, emerging research, inclusive of our findings, unveils PCSK9’s potential role as a pivotal indicator for cancer prognosis and its prospective application as a transformative target for cancer treatment." (PMID 38185721, 2024). "While the essence of PCSK9 in these cancers still remains unclear, PCSK9 could potentially act as a valuable biomarker for evaluating clinical outcomes in patients with these cancers." (PMID 38185721, 2024). "Ezetimibe, omega 3-fatty acids, fibrates and inhibitors of proprotein convertase subtilisin/kexin type 9 (PCSK9) may enhance the regulation of lipid homeostasis, as demonstrated in other cancers." (PMID 38509261, 2024). "This underscores the importance of PCSK9 in the orchestration of cancer immunity." (PMID 38185721, 2024). "PCSK9 is involved in the regulation of diverse proteins and signaling pathways in cancer." (PMID 38822303, 2024). "Moreover, in recent studies, it has also been demonstrated that PCSK9 plays a regulatory role in proliferation and apoptosis in human cancer cells." (PMID 38473748, 2024). "Another study knocked out the PCSK9 gene in four malignant mouse cancer cell lines (B16F10, 4T1, MC38, and CT26) using CRISPR-Cas9 technology, and tumor growth was significantly attenuated or blocked in mice in a CTL-dependent manner and the efficacy of PD-1 inhibitors was enhanced." (PMID 39736777, 2024). "Identifying the specific enzymes affected by intracellular PCSK9 could provide valuable guidance on whether suppressing PCSK9-mediated CYP450 inhibition is beneficial for cancer treatment." (PMID 39138259, 2024). "However, the PCSK9 gene is also expressed in multiple organs, including liver, kidney, small intestine, and cancer cells." (PMID 38887452, 2024). "This review provides an overview of the current insights into the role of PCSK9 in cholesterol metabolism and cancer biology and discuss the potential benefits and challenges of combining PCSK9 inhibition with anti-PD-1/PD-L1 immunotherapy for cancer treatment." (PMID 39324018, 2024). "Additional therapeutic strategies aiming at PCSK9 inhibition, such as ASOs, adnectin, anticalin, pseurotin A (PS), and various natural products, have been delineated and show profound potential for inhibiting PCSK9 function across cellular and animal cancer models." (PMID 38185721, 2024). "Collectively, these results may provide new ideas for developing potential drugs relating to the expression of PCSK9 for treating cancers." (PMID 37860186, 2023). "Abnormal PCSK9 expression has been reported in various cancer types." (PMID 37860186, 2023). "First, we describe how PCSK9 is involved in cancer progression and immune escape." (PMID 36900189, 2023). "Furthermore, our examination of the pan-cancer population highlighted a correlation between PCSK9 expression and CD8+ T cell subpopulations in LIHC and LUAD." (PMID 37860186, 2023). "Cancer patients who develop ICIs-related ASCVD could benefit from PCSK9 inhibition therapy in order to reduce atherosclerotic events, cardiovascular mortality, and improve overall survival." (PMID 36900189, 2023). "In addition to its reported function in cancer, we discovered that flubendazole can inhibit the expression of PCSK9 via direct interactions." (PMID 37151886, 2023).
cancer (continued). "Therefore, PCSK9 regulation in physiological processes such as cancer cell death and cell proliferation is in addition to its role in cholesterol homeostasis." (PMID 37860186, 2023). "Intensive low‐density lipoprotein cholesterol lowering with a proprotein convertase subtilisin/kexin type 9 inhibitor combined with statin does not appear to increase the risk of new or worsening cancer events." (PMID 37458138, 2023). "Based on this, it is conceivable that a target population that could benefit from PCSK9 therapy are cancer patients treated with ICIs therapies, especially those with confirmed ASCVD." (PMID 36900189, 2023). "PCSK9 could serve as a robust prognostic pan-cancer biomarker given its correlation with immune infiltrates in different cancer types, thus potentially highlighting a new direction for targeted clinical therapy of cancers." (PMID 37860186, 2023). "This study has provided a more comprehensive analysis of PCSK9 expression in cancer." (PMID 37860186, 2023). "Other cancers exhibited a protective role for PCSK9 with low expression, such as BRCA (OS, HR = 0.58, p = 0.001; RFS, HR = 0.64, p = 0.047), UCS (OS, HR = 0.61, p = 0.022; RFS, HR = 0.56, p = 0.044), ESCA (RFS, HR = 0.26, p = 0.013), and HNSC (RFS, HR = 0.26, p = 0.007)." (PMID 37860186, 2023). "PCSK9 that is overexpressed in human cancers was shown to suppress antitumor T cell immunity." (PMID 36909826, 2023). "Above all, these findings strongly suggest that PCSK9 could be a future cancer immunotherapy target based on the interaction of immune cells in multiple cancer types." (PMID 37860186, 2023). "Thus, a preliminary assessment of the PsA acute toxicity represents the steppingstone to develop PsA as a novel orally active PCSK9 axis modulating cancer recurrence inhibitor." (PMID 36771126, 2023). "Additionally, the PCSK9-induced degradation of MHC-I receptors paved the way to the use of PCSK9 inhibitors as adjuvants to immunotherapies targeting various cancers." (PMID 36851576, 2023). "Due to the integral role of PCSK9 in lipid metabolism, PCSK9 function and its inhibition could potentially influence cancer pathophysiology." (PMID 37458138, 2023). "Our study also identified an association between PCSK9 inhibitors and lower IGF‐1, which may indicate a decrease in cancer risk, since IGF‐1 is implicated in the growth and proliferation of cancer cells." (PMID 37208559, 2023). "The results revealed dysregulated PCSK9 expression in different cancers." (PMID 37860186, 2023). "Our study indicated that PCSK9 was a significant prognostic factor in various cancer types." (PMID 37860186, 2023). "In this report, we show that substantial LDL‐C lowering with a PCSK9 inhibitor added to background statin therapy does not affect the risk of new or worsening cancer over the course of 2.5 years of median follow‐up." (PMID 37458138, 2023). "This may shed light on the ineffectiveness of the PCSK9 vaccine in mice and of targeting circulating PCSK9 in cancer patients." (PMID 36588164, 2023). "Moreover, PCSK9 induces peripheral immune tolerance (inhibition of cancer cell- immune recognition), reduces cardiac mitochondrial metabolism, and enhances cancer cell survival." (PMID 36900189, 2023). "This knowledge is essential in developing PCSK9-based cancer therapy." (PMID 36588164, 2023). "Samples from the cancer regions compared to normal areas showed increased levels of PCSK9." (PMID 37765005, 2023). "Also, we discuss how suppressing PCSK9 leads to the MHC-1 accumulation on the surface of cancer cells, which results in T lymphocyte invasion." (PMID 38864086, 2023). "We demonstrated that PCSK9 is frequently altered across different cancer types." (PMID 37860186, 2023). "The results showed that different factors could to some extent explain the heterogeneity of cancers that may have led to a protective or detrimental PCSK9 prognostic relationship." (PMID 37860186, 2023).
cancer (continued). "Therefore, PCSK9 inhibition is a new and hopeful approach to augment the immune checkpoint for cancer treatment." (PMID 37055467, 2023). "PCSK9 has progressively proven to be a universal target in cancer." (PMID 37103355, 2023). "Accordingly, these results indicated that PCSK9 may mediate tumorigenesis by regulating DNA damage or methylation status in human cancers." (PMID 37860186, 2023). "Previous studies on PCSK9 expression in cancer used several research methods, such as DNA microarrays, but were limited to relatively small sample sizes and limited numbers of cancer types." (PMID 37860186, 2023). "Recent preclinical and clinical studies focused on SGLT-2 inhibitors, PCSK9 inhibitors, sacubitril-valsartan and selective cytokine inhibitors have demonstrated some beneficial cardiorenal effects in non-cancer and cancer patients treated with cardiotoxic drugs." (PMID 36547420, 2022). "Targeting PCSK9 to treat cancer becomes attractive not only because of its critical role in lipid metabolism but also because of its growing place in the recent literature, which has reported its tight association with the incidence and progression of several cancers." (PMID 36611859, 2022). "Meanwhile, inhibiting PCSK9 effectively enhances PD-1 inhibitor therapy for cancers." (PMID 36110953, 2022). "At this time, there are no long-term studies evaluating the effect of PCSK9 MABs in reducing CVD risk factors in cancer survivors, though is likely a new emerging area for research." (PMID 36158986, 2022). "In fact, anti-PCSK9 therapies (e.g. Repatha) have already been developed and used in the clinic to treat cardiovascular disease and thus could be repurposed to target cancer." (PMID 39872079, 2022). "As per our results, PCSK9 may now modulate cancer survival and resistance by an additional mechanism connected to anti-oxidative housekeeping activities." (PMID 36611859, 2022). "Similar research has been conducted in cancer cells and found that PCSK9 inhibition could restore the levels of surface MHC-I of cancer cells to guarantee antigen presentation and CD8+ lymphocytic infiltration." (PMID 39872079, 2022). "The use of PCSK-9 inhibitors in patients with cancer is less well-studied, though early basic science evidence suggests that their cholesterol-related and non-cholesterol-related properties may have consequences for cancer as well." (PMID 36017084, 2022). "Furthermore, a potential positive role for PCSK9 in other pathological processes that require a pro-inflammatory profile of Mφ, as occurs in cancer, cannot be disregarded." (PMID 36012389, 2022). "So far, we observed a high expression of PCSK9 in the majority of cancers, suggesting that targeting it could serve as an effective anticancer strategy." (PMID 36552895, 2022). "PCSK9 has proven to be a key player in multiple physiological and pathological conditions, whether that includes cancer development, immunity or even normal organ function." (PMID 36552895, 2022). "At this juncture, there is insufficient evidence to recommend PCSK-9 inhibitors as adjunct therapy for cancer survivors unless they have an indication specified in society guidelines, but further research is needed to explore specific indications for this medication in cancer survivors." (PMID 36017084, 2022). "We present a comprehensive assessment of the different strategies targeting PCSK9 and show how these approaches could be extended to future therapeutic options to treat cancers with a main focus on the liver." (PMID 36552895, 2022). "In our study, we observed that targeting PCSK9 expression impaired OC cell survival, suggesting that one way to efficiently kill PCSK9-expressing cancer cells is via its inhibition and this approach should be investigated in clinical trials in a similar way as statins." (PMID 34359627, 2021). "Moreover, clinically approved PCSK9-neutralizing antibodies were found to synergize with anti-PD1 therapy in suppressing tumor growth in mouse models of cancer." (PMID 34504788, 2021).
cancer (continued). "Due to poor data on effectiveness and safety of PCSK9 inhibitors in cancer, the impact of PCSK9 inhibition in these pathological conditions is still unknown (P)." (PMID 34504788, 2021). "PCSK9 inhibitor PF-06446846 had a clear effect on cell proliferation at 100μM concentration in HeLa, OVCAR3 and OVCAR3cis cells, whereas JHSO2 cells that do not express PCSK9 showed minimal sensitivity (85% cell survival), indicating that PCSK9 plays a survival role in these cancer cells." (PMID 34359627, 2021). "Therefore, studies have been carried out in animal models to determine the effect of administering a vaccine to stimulate the immune system to produce antibodies against the PCSK-9 molecule on the development of certain types of cancer." (PMID 33808697, 2021). "In addition to its therapeutic role in regulating cholesterol levels, PCSK9 has been previously shown to be involved in cancer." (PMID 34359627, 2021). "Our results show that targeting PCSK9 expression could impair OC cell survival, which warrants further investigation to address the dependency of this cancer on lipogenesis and omental metastasis." (PMID 34359627, 2021). "Next, we investigated whether targeting PCSK9 with a specific inhibitor would similarly impair cancer cell survival." (PMID 34359627, 2021). "It was still controversial whether serum cholesterol influenced to cancer, but in terms of PCSK9 and cancer several reported were documented." (PMID 34504788, 2021). "Although it is currently unclear whether this will lead to new therapeutic options against specific types of cancer in future, it is clear that it is mechanistically very interesting, showing quite different roles for PCSK9 in different organs." (PMID 33364976, 2020). "New experimental evidences propose an active role of PCSK9 in cancer onset and progression." (PMID 30787312, 2019). "Several studies highlight the involvement of PCSK9 in imparting advantages to certain cancer types." (PMID 30386595, 2018). "Thus, the advanced phase III clinical trial using PCSK9 inhibitors is in a better situation to assess long term safety, and would register the incidence of many cancers including liver." (PMID 26674961, 2015). "This allows for a potential additional cancer therapy via PCSK9 inhibitors.." (PMID 24669769, 2014). "Beyond LRP1 suppression, experimental data indicate that PCSK9 could contribute to cancer progression by promoting epithelial–mesenchymal transition (EMT), activating the PI3K/AKT signalling pathway, and influencing macrophage polarisation toward pro-inflammatory and pro-metastatic phenotypes." (PMID 41008547, 2025). "However, emerging evidence suggests that PCSK9 may have broader biological functions, including the roles in immune modulation and cancer progression." (PMID 39872986, 2025). "Additionally, some research suggests that PCSK9 inhibitors may reduce cancer cell proliferation by altering cholesterol availability, which is essential for membrane synthesis and cellular signaling in rapidly dividing tumor cells." (PMID 40364115, 2025). "Moreover, PCSK9 may also influence the metabolic adaptation of cancer cells in distinct microenvironments." (PMID 41008547, 2025). "Thus, PCSK9 is a promising target for cancer immunotherapy and combinatorial treatment." (PMID 38600469, 2024). "However, a comprehensive pan-cancer analysis of PCSK9 has yet to be conducted." (PMID 38600469, 2024). "Consequently, PCSK9-targeting agents, such as anti-PCSK9 antibodies, vaccines, antisense RNAi, and some drugs (acRoots, lupin peptides, and pseurotin A) have been developed to target the regulation of PCSK9 for potential cancer treatment strategies." (PMID 38617549, 2024). "Notably, PCSK9 is not only expressed by cancer cells but is also released by them." (PMID 38473748, 2024). "Therefore, PCSK9 inhibition might offer a novel strategy for preventing and treating cancer by modulating cholesterol metabolism." (PMID 39324018, 2024).